ARRB2 (arrestin beta 2)
Description:
Functions in regulating agonist-mediated G protein-coupled receptor (GPCR) signaling by mediating both receptor desensitization and resensitization processes. During homologous desensitization, beta-arrestins bind to the GPCR-phosphorylated receptor and sterically preclude its coupling to the cognate G protein; the binding appears to require additional receptor determinants exposed only in the active receptor conformation. The beta-arrestins target many receptors for internalization by acting as endocytic adapters (CLASPs, clathrin-associated sorting proteins) and recruiting the GPRCs to the adapter protein 2 complex 2 (AP-2) in clathrin-coated pits (CCPs). However, the extent of beta-arrestin involvement appears to vary significantly depending on the receptor, agonist and cell type. Internalized arrestin-receptor complexes traffic to intracellular endosomes, where they remain uncoupled from G proteins. Two different modes of arrestin-mediated internalization occur. Class A receptors, like ADRB2, OPRM1, ENDRA, D1AR and ADRA1B dissociate from beta-arrestin at or near the plasma membrane and undergo rapid recycling. Class B receptors, like AVPR2, AGTR1, NTSR1, TRHR and TACR1 internalize as a complex with arrestin and traffic with it to endosomal vesicles, presumably as desensitized receptors, for extended periods of time. Receptor resensitization then requires that receptor-bound arrestin is removed so that the receptor can be dephosphorylated and returned to the plasma membrane. Mediates endocytosis of CCR7 following ligation of CCL19 but not CCL21. Involved in internalization of P2RY1, P2RY4, P2RY6 and P2RY11 and ATP-stimulated internalization of P2RY2. Involved in phosphorylation-dependent internalization of OPRD1 and subsequent recycling or degradation. Involved in ubiquitination of IGF1R. Beta-arrestins function as multivalent adapter proteins that can switch the GPCR from a G protein signaling mode that transmits short-lived signals from the plasma membrane via small molecule second messengers and ion channels to a beta-arrestin signaling mode that transmits a distinct set of signals that are initiated as the receptor internalizes and transits the intracellular compartment. Acts as a signaling scaffold for MAPK pathways such as MAPK1/3 (ERK1/2) and MAPK10 (JNK3). ERK1/2 and JNK3 activated by the beta-arrestin scaffold are largely excluded from the nucleus and confined to cytoplasmic locations such as endocytic vesicles, also called beta-arrestin signalosomes. Acts as a signaling scaffold for the AKT1 pathway. GPCRs for which the beta-arrestin-mediated signaling relies on both ARRB1 and ARRB2 (codependent regulation) include ADRB2, F2RL1 and PTH1R. For some GPCRs the beta-arrestin-mediated signaling relies on either ARRB1 or ARRB2 and is inhibited by the other respective beta-arrestin form (reciprocal regulation). Increases ERK1/2 signaling in AGTR1- and AVPR2-mediated activation (reciprocal regulation). Involved in CCR7-mediated ERK1/2 signaling involving ligand CCL19. Is involved in type-1A angiotensin II receptor/AGTR1-mediated ERK activity. Is involved in type-1A angiotensin II receptor/AGTR1-mediated MAPK10 activity. Is involved in dopamine-stimulated AKT1 activity in the striatum by disrupting the association of AKT1 with its negative regulator PP2A. Involved in AGTR1-mediated chemotaxis. Appears to function as signaling scaffold involved in regulation of MIP-1-beta-stimulated CCR5-dependent chemotaxis. Involved in attenuation of NF-kappa-B-dependent transcription in response to GPCR or cytokine stimulation by interacting with and stabilizing CHUK. Suppresses UV-induced NF-kappa-B-dependent activation by interacting with CHUK. The function is promoted by stimulation of ADRB2 and dephosphorylation of ARRB2. May serve as nuclear messenger for GPCRs. Upon stimulation of OR1D2, may be involved in regulation of gene expression during the early processes of fertilization. Also involved in regulation of receptors other than GPCRs. Involved in endocytosis of TGFBR2 and TGFBR3 and down-regulates TGF-beta signaling such as NF-kappa-B activation. Involved in both localization to primary cilium and endocytosis of smoothened (SMO) in a GRK2-dependent process. Involved in endocytosis of SLC9A5. Involved in endocytosis of ENG and subsequent TGF-beta-mediated ERK activation and migration of epithelial cells. Involved in Toll-like receptor and IL-1 receptor signaling through the interaction with TRAF6 which prevents TRAF6 autoubiquitination and oligomerization required for activation of NF-kappa-B and JUN. Involved in insulin resistance by acting as insulin-induced signaling scaffold for SRC, AKT1 and INSR. Involved in regulation of inhibitory signaling of natural killer cells by recruiting PTPN6 and PTPN11 to KIR2DL1. Involved in IL8-mediated granule release in neutrophils. Involved in the internalization of the atypical chemokine receptor ACKR3. Acts as an adapter protein coupling FFAR4 receptor to specific downstream signaling pathways, as well as mediating receptor endocytosis. During the activation step of NLRP3 inflammasome, directly associates with NLRP3 leading to inhibition of pro-inflammatory cytokine release and inhibition of inflammation.
Synonyms: ARB2; ARR2; BARR2; DKFZp686L0365
Tractability: Antibody: its Gene Ontology location is reachable by antibodies, with high confidence; UniProt places it where antibodies can reach, with medium confidence; the Human Protein Atlas places it where antibodies can reach. PROTAC: UniProt records ubiquitination sites on it; ubiquitination databases record sites on it; its protein half-life has been measured.
Safety:
Unwanted effects reported when the protein is acted on. In parentheses: how it was acted on, where the effect was seen, and who reports it.
addiction (source: ClinPGx)
adverse events (source: ClinPGx)
Gene: Protein-coding gene on chromosome 17 (4,710,393 to 4,721,500, forward strand). Ensembl gene ENSG00000141480.
Subcellular location: Cytoplasm; Nucleus; Cell membrane; Membrane, clathrin-coated pit; Cytoplasmic vesicle
Subcellular location (Human Protein Atlas): Cytosol; Plasma membrane; Nucleoplasm
Pathways (Reactome):
Disease: Paradoxical activation of RAF signaling by kinase inactive BRAF; Signaling by BRAF and RAF1 fusions; Signaling by RAF1 mutants; Signaling by high-kinase activity BRAF mutants; Signaling by moderate kinase activity BRAF mutants; Signaling downstream of RAS mutants
Signal Transduction: Activated NOTCH1 Transmits Signal to the Nucleus; Activation of SMO; G alpha (s) signalling events; MAP2K and MAPK activation; TGFBR3 regulates TGF-beta signaling; WNT5A-dependent internalization of FZD4
Vesicle-mediated transport: Cargo recognition for clathrin-mediated endocytosis; Clathrin-mediated endocytosis
Hemostasis: Thrombin signalling through proteinase activated receptors (PARs)
Metabolism of proteins: Ub-specific processing proteases
Gene Ontology:
Molecular function: angiotensin receptor binding; D1 dopamine receptor binding; enzyme binding; G protein-coupled receptor binding; molecular adaptor activity; protein binding; protein-macromolecule adaptor activity; signaling receptor binding; ubiquitin protein ligase binding; protein kinase B binding
Biological process: cell chemotaxis; chemokine-mediated signaling pathway; desensitization of G protein-coupled receptor signaling pathway; G protein-coupled receptor internalization; negative regulation of canonical NF-kappaB signal transduction; negative regulation of natural killer cell mediated cytotoxicity; positive regulation of ERK1 and ERK2 cascade; positive regulation of receptor internalization; proteasome-mediated ubiquitin-dependent protein catabolic process; protein ubiquitination; receptor internalization; transcription by RNA polymerase II; transforming growth factor beta receptor signaling pathway; beta-arrestin-dependent dopamine receptor signaling pathway; excitatory postsynaptic potential; modulation of chemical synaptic transmission; negative regulation of phosphatidylinositol 3-kinase/protein kinase B signal transduction; positive regulation of cardiac muscle hypertrophy; positive regulation of smoothened signaling pathway; protein localization to non-motile cilium; sensory perception of pain; adult walking behavior; negative regulation of interleukin-1 beta production; negative regulation of interleukin-12 production; negative regulation of interleukin-6 production; and 9 more
Cellular component: cytoplasm; cytoplasmic vesicle; cytosol; endocytic vesicle; nucleus; plasma membrane; endocytic vesicle membrane; clathrin-coated pit; glutamatergic synapse; postsynapse
Genetic constraint (gnomAD): Loss-of-function variants: 21 observed, 53.79 expected, observed/expected ratio (o/e) 0.39, 90% interval 0.28 to 0.56. The upper end of that interval is the gene's LOEUF score, 0.56, which puts it in group 2 of 6, group 1 being the genes least tolerant of losing a copy. Missense variants: 366 observed, 533.34 expected, observed/expected ratio (o/e) 0.69, 90% interval 0.63 to 0.75. Synonymous variants: 180 observed, 216.95 expected, observed/expected ratio (o/e) 0.83, 90% interval 0.73 to 0.94.
Homologues: Orthologues: chimpanzee ARRB2 (99% identical), pig ARRB2 (98% identical), dog ARRB2 (97% identical), mouse Arrb2 (97% identical), rat Arrb2 (96% identical), guinea pig ARRB2 (95% identical), macaque ARRB2 (94% identical), zebrafish arrb2b (84% identical), zebrafish arrb2a (82% identical), tropical clawed frog arrb2 (80% identical), Drosophila melanogaster krz (59% identical), Caenorhabditis elegans arr-1 (54% identical). Paralogues in human: ARRB1 (77% identical), ARR3 (53% identical), SAG (53% identical).
Diseases named in the same sentence as ARRB2 in open-access papers:
ARRB2 is named in the same sentence as 86 diseases in open-access papers, as found by Europe PMC text mining. Sharing a sentence is not in itself a finding about the gene and the disease. The quoted sentences say what the papers report.
retinal degeneration (10 papers, 2012 to 2025). Degeneration of the retina. "The additional candidate gene is ARRB2, arrestin beta 2, which is involved in retinal degeneration in Drosophila." (PMID 24777202, 2014).
prostate carcinoma (8 papers, 2020 to 2024). A carcinoma that arises from epithelial cells of the prostate gland. "ARRB2 (β-arrestin 2) expression has been shown to modulate the growth of colorectal cancer, glioblastoma, lung cancer, ovarian cancer, and prostate cancer." (PMID 39062749, 2024). "Downregulation of ARRB2 promotes lung and prostate cancer growth." (PMID 37783676, 2023).
lung carcinoma (6 papers, 2018 to 2024). "ARRB2 variants have been previously linked to smoking status, and the depletion of the gene promoted lung cancer growth in a mouse model." (PMID 37742993, 2023). "Based on these results, we evaluated the possibility that ARRB2 might be functionally implicated in lung cancer progression specifically regulated by TLRs-induced autophagy." (PMID 37443143, 2023). "The aim of this study was to determine the functional role of ARRB2 in lung cancer progression through the cross-talk between autophagy and TLR-mediated signaling." (PMID 37443143, 2023). "Taken together, these results suggest that ARRB2 can functionally inhibit the migration, invasion, colony formation, and proliferation of lung cancer cells induced by TLR3 and TLR4 stimulation." (PMID 37443143, 2023). "Nevertheless, the molecular and cellular mechanisms by which ARRB2 participates in lung cancer progression are poorly understood." (PMID 37443143, 2023). "Altogether, our current data suggest that ARRB2 can negatively regulate lung cancer progression by inhibiting TLR3- and TLR4-induced autophagy." (PMID 37443143, 2023). "ARRB2 expression was significantly down-regulated in lung cancers." (PMID 37443143, 2023). "Consequently, ARRB2 can inhibit lung cancer progression regulated by two signaling axes, TRAF6-TAB2 signaling axis for NF-κB activation and the TRAF6-BECN1 signaling axis for autophagy induction, in response to TLR3 and TLR4 stimulation." (PMID 37443143, 2023). "Notably, ARRB2-knockout (ARRB2KO) lung cancer cells exhibited marked enhancements of cancer migration, invasion, colony formation, and proliferation in response to TLR3 and TLR4 stimulation." (PMID 37443143, 2023). "We experimentally determined molecular and cellular mechanisms by which ARRB2 could regulate lung cancer progression." (PMID 37443143, 2023). "Overall survival of LUAD patients was worse for those with low ARRB2 expression (low ARRB2 vs. high ARRB2, p = 0.0094), indicating a negative association of ARRB2 expression in lung cancer." (PMID 37443143, 2023). "In this study, we demonstrated that ARRB2, a multifunctional cellular adaptor protein capable of regulating cellular signaling pathways, could functionally regulate lung cancer progression induced by TLR3 and TLR4 through inhibition of NF-κB and autophagy." (PMID 37443143, 2023). "Importantly, the logical background and initiative idea of the functional role of ARRB2 in lung cancer could be found in TCGA data and microarray data of NSCLC patients (n = 37)." (PMID 37443143, 2023). "Notably, ubiquitination levels of BECN1 and TRAF6 were remarkably enhanced in ARRB2KO lung cancer cells, strongly indicating that ARRB2 could inhibit the TRAF6-BECN1 signaling axis for autophagy induction." (PMID 37443143, 2023). "Next, we examined whether ARRB2 was involved in lung cancer progression induced by TLR3 and TLR4." (PMID 37443143, 2023). "After elucidating the molecular mechanism of β-arrestin 2 (ARRB2), we generated ARRB2-knockout (ARRB2KO) lung cancer cells using CRISPR/Cas9 gene-editing method (two vector-based systems)." (PMID 37443143, 2023). "Given the molecular mechanism by which ARRB2 inhibited the TRAF6-related signaling axis for the activation of NF-κB and autophagy induction, we verified the functional role of ARRB2 in lung cancer progression." (PMID 37443143, 2023). "To obtain insight into the role of ARRB2 in lung cancer, we obtained lung tumor tissues (LTTs) and matched lung normal tissues (mLNTs) from non-small cell lung cancer (NSCLC) patients (n = 37)." (PMID 37443143, 2023). "Our results also demonstrate that ARRB2 can negatively regulate the TRAF6-TAB2 signaling axis for NF-κB activation and the TRAF6-BECN1 signaling axis for autophagy induction, thereby attenuating lung cancer progression induced by TLR3 and TLR4." (PMID 37443143, 2023).
lung carcinoma (continued). "Based on these results, we determined whether ARRB2 could negatively regulate autophagy induced by TLR signals through the regulation of TRAF6 ubiquitination, thereby inhibiting the migration and invasion of lung cancer." (PMID 37443143, 2023).
Alzheimer disease (5 papers, 2020 to 2025). A progressive, neurodegenerative disease characterized by loss of function and death of nerve cells in several areas of the brain leading to loss of cognitive function such as memory and language. "Perhaps a more interesting ontological category is the 11 downregulated genes associated with MAPK signaling pathway, a number of which (Arrb2, Cacna1g, Fgfr4, Taok1, Cacna1h) have been implicated in Alzheimer's disease (AD)." (PMID 33282900, 2020). "Additionally, ARRB2 is associated with a variety of neurological disorders, such as Parkinson's disease, depressive behavior, and Alzheimer's disease." (PMID 33204724, 2020). "ARRB2 levels is a potential biomarker for depression and Alzheimer’s disease." (PMID 34394017, 2021). "For instance, in brain, ARRB2 regulates Aβ generation and γ‐secretase activity in Alzheimer disease, and overexpression or activation of ARRB1, but not ARRB2, exerts neuroprotection through coordination of BECN‐1‐dependent autophagy in cerebral ischaemia." (PMID 32445435, 2020).
liver fibrosis (4 papers, 2018 to 2023). "Recently, several studies revealed that multifunctional protein β-arrestin 2 (Arrb2) modulated cell apoptosis in liver fibrosis and HCC, but its role in ALD has not been fully understood." (PMID 30283336, 2018). "For instance, Arrb2 promotes hepatocyte apoptosis in bile duct ligation (BDL) while blocking hepatic stellate cells (HSCs) apoptosis in liver fibrosis." (PMID 30283336, 2018). "To investigate whether Asp regulates liver fibrosis by regulating the NLRP3 signal, we first validated the role of NLRP3 and ARRB2 on liver fibrosis to further evaluate the role of the inflammasome in hepatic fibroblast activation." (PMID 36983568, 2023). "When NLRP3 or ARRB2 was successfully silenced, as detected using real-time qPCR and Western blot, we analyzed the mRNA and protein levels of genes related to inflammation and liver fibrosis, including IL-1β, IL-18, p-NF-κB, COL III, FN, and α-SMA in LX-2 cells." (PMID 36983568, 2023).
ovarian carcinoma (4 papers, 2020 to 2024). A malignant neoplasm originating from the surface ovarian epithelium. "ARRB2 has been reported to play important roles in the progression of ovarian cancer, renal cell carcinoma, and intestinal tumors." (PMID 38341429, 2024). "Therefore, TCGA data were used to analyze the expression of β-arrestin genes ARRB1 and ARRB2 and the survival of patients with ovarian cancer." (PMID 36969037, 2023).
respiratory depression (4 papers, 2018 to 2025). A decrease in ventilation secondary to impaired signals from the central nervous system. "The core premise for the development of MOR biased agonists is that Arrb2-dependent signaling provides a molecular mechanism to dissociate analgesia from respiratory depression." (PMID 34002697, 2021). "Such a possibility emerged in 2005 when it was reported that mice with germline deletion of ß-arrestin 2 (Arrb2-/-) experience enhanced analgesia with attenuated respiratory depression when administered systemic morphine." (PMID 34002697, 2021). "Indeed, all three pathways have been implicated in OIRD but a role for Arrb2 has been suggested to be important and selective for respiratory depression, relative to analgesia." (PMID 34002697, 2021). "Our data, together with another recent report, does not show a role of Arrb2 in opioid-induced respiratory depression and suggests that MOR biased agonists attenuate OIRD through a different mechanism." (PMID 34002697, 2021).